STX17 (syntaxin 17)
Description:
SNAREs, soluble N-ethylmaleimide-sensitive factor-attachment protein receptors, are essential proteins for fusion of cellular membranes. SNAREs localized on opposing membranes assemble to form a trans-SNARE complex, an extended, parallel four alpha-helical bundle that drives membrane fusion. STX17 is a SNARE of the autophagosome involved in autophagy through the direct control of autophagosome membrane fusion with the lysosome membrane. May also play a role in the early secretory pathway where it may maintain the architecture of the endoplasmic reticulum-Golgi intermediate compartment/ERGIC and Golgi and/or regulate transport between the endoplasmic reticulum, the ERGIC and the Golgi.
Synonyms: FLJ20651
Tractability: Antibody: UniProt predicts a signal peptide or a membrane-spanning region; its Gene Ontology location is reachable by antibodies, with medium confidence. PROTAC: ubiquitination databases record sites on it; its protein half-life has been measured.
Gene: Protein-coding gene on chromosome 9 (99,906,654 to 99,974,534, forward strand). Ensembl gene ENSG00000136874.
Subcellular location: Endoplasmic reticulum membrane; Smooth endoplasmic reticulum membrane; Endoplasmic reticulum-Golgi intermediate compartment membrane; Cytoplasmic vesicle, autophagosome membrane; Cytoplasmic vesicle, COPII-coated vesicle membrane; Cytoplasm, cytosol; Mitochondrion membrane; Autolysosome membrane
Subcellular location (Human Protein Atlas): Cytosol; Nucleoli
Pathways (Reactome):
Vesicle-mediated transport: COPII-mediated vesicle transport
Gene Ontology:
Molecular function: protein binding; protein phosphatase binding; SNAP receptor activity; SNARE binding; protein kinase binding
Biological process: autophagosome maturation; autophagosome membrane docking; autophagosome-lysosome fusion; endoplasmic reticulum to Golgi vesicle-mediated transport; endoplasmic reticulum-Golgi intermediate compartment organization; Golgi organization; protein localization to phagophore assembly site; cellular response to starvation; exocytosis; macroautophagy; vesicle fusion; intracellular protein transport; vesicle-mediated transport
Cellular component: autolysosome membrane; autophagosome; autophagosome membrane; endoplasmic reticulum membrane; endoplasmic reticulum-Golgi intermediate compartment; endoplasmic reticulum-Golgi intermediate compartment membrane; HOPS complex; lysosomal membrane; mitochondria-associated endoplasmic reticulum membrane contact site; mitochondrial membrane; mitochondrion; rough endoplasmic reticulum; SNARE complex; COPII-coated ER to Golgi transport vesicle; cytosol; membrane fusion priming complex; smooth endoplasmic reticulum membrane; cytoplasm; ER to Golgi transport vesicle membrane; membrane
Genetic constraint (gnomAD): Loss-of-function variants: 28 observed, 35.46 expected, observed/expected ratio (o/e) 0.79, 90% interval 0.58 to 1.08. The synonymous counts are far from expectation, so gnomAD's model fits this gene poorly and the ratio says little. Missense variants: 312 observed, 362.62 expected, observed/expected ratio (o/e) 0.86, 90% interval 0.78 to 0.94. Synonymous variants: 92 observed, 123.29 expected, observed/expected ratio (o/e) 0.75, 90% interval 0.63 to 0.89.
Homologues: Orthologues: chimpanzee STX17 (100% identical), macaque STX17 (99% identical), rabbit STX17 (97% identical), dog STX17 (96% identical), pig STX17 (95% identical), mouse Stx17 (92% identical), rat Stx17 (91% identical), guinea pig STX17 (89% identical), zebrafish stx17 (53% identical), Drosophila melanogaster Syx17 (30% identical), Caenorhabditis elegans syx-17 (16% identical). Paralogues in human: STX1A (20% identical), STX1B (20% identical), STX12 (17% identical), STX3 (17% identical), STX2 (17% identical), STX19 (16% identical), STX4 (16% identical), STX7 (16% identical), STX5 (14% identical), STX11 (13% identical), TSNARE1 (13% identical), STX16 (11% identical).
Diseases named in the same sentence as STX17 in open-access papers:
STX17 is named in the same sentence as 48 diseases in open-access papers, as found by Europe PMC text mining. Sharing a sentence is not in itself a finding about the gene and the disease. The quoted sentences say what the papers report.
melanoma (17 papers, 2012 to 2024). A malignant, usually aggressive tumor composed of atypical, neoplastic melanocytes. "This article narratively reviews the role of some genetic features related to melanoma formation in horses, such as STX17 mutation, ASIP or MITF alterations, and the link between the graying process and the development of these tumors." (PMID 36670786, 2023). "An intronic mutation in the STX17 (syntaxin-17) gene was identified as a link to the grey horse phenotype and predisposition to melanoma." (PMID 32024502, 2020). "It has also been found that gray hair phenotype is caused by a 4.6-kb duplication in the STX17 gene constituting a cis-acting regulatory mutation, causing susceptibility to melanoma." (PMID 31316551, 2019). "The allele status of STX17 influences the progression of greying by age, grade of speckling (pigmentation among grey hair), grade of vitiligo and incidences and grade of melanoma." (PMID 30836959, 2019). "For example mutations in α-keratin (KRT75) produce the pleiotropic effects in chicken and a cis-acting regulatory mutation in intron 6 of STX17 (syntaxin-17) is responsible for the pigmentation and melanoma susceptibility phenotypes in horse." (PMID 26100605, 2015). "On the other side, we were able to show that estimated genetic correlation between melanoma and vitiligo was negligible after accounting for the pleiotropic effect of STX17 mutation." (PMID 23408897, 2013). "The dominant phenotype of greying with age in horses, caused by a 4.6-kb duplication in intron 6 of STX17, is associated with a high incidence of melanoma and vitiligo-like skin depigmentation." (PMID 23408897, 2013). "Why does the copy number expansion of the 4.6 kb STX17 sequence predispose to melanomas in horses?" (PMID 38571883, 2024). "STX17 is a causative gene for melanoma tissue in grey horses." (PMID 31940795, 2020). "We have previously demonstrated that the causative mutation for the Grey horse phenotype encompassing the dramatically increased risk of melanoma development is a 4.6 kb duplication in intron 6 of Syntaxin 17 (STX17) (; referred to as Grey mutation thereafter)." (PMID 25413220, 2014). "The elevated copy number in tumour DNA compared with constitutional DNA constitutes the first set of proof that the duplication in STX17 not only predisposes to melanoma development, but that copy number expansion of the duplicated sequence may be a driving force in melanoma development." (PMID 22857264, 2012). "Expression analysis using grey horse melanomas showed that both STX17 and the neighbouring gene NR4A3 show upregulated expression from the Grey allele in heterozygous horses." (PMID 38571883, 2024). "Expression analysis of Grey horse melanoma tissue first demonstrated that both STX17 and NR4A3 show upregulated expression from the Grey chromosome in heterozygotes." (PMID 38571883, 2024). "The Grey mutation is associated with upregulated expression of both Syntaxin 17 and the neighbouring NR4A3 gene in Grey horse melanomas." (PMID 38571883, 2024). "Elevated STX17 is associated with constitutive activation of the ERK pathway in melanocytic cells, thus highlighting the similarities to human melanoma in which the MAPK/ERK pathway is also involved." (PMID 32652526, 2020). "The 4.6-kb duplication in the intron of the syntaxin 17 (STX17) gene was found to cause the graying in horses and is associated with a high incidence of melanoma and vitiligo-like skin depigmentation." (PMID 31717496, 2019). "Finally, we graphically illustrated the genetic relationship among melanoma grade, grey level, vitiligo grade and speckling grade with respect to STX17 genotype." (PMID 23408897, 2013). "While STX17 explains large proportions of the phenotypic variance, we were surprised to see that, when only the data from homozygous GG horses were analysed, the residual polygene component still explained a large part of the variation in melanoma and vitiligo grade." (PMID 23408897, 2013).
melanoma (continued). "Syntaxin 17 is a SNARE protein with a critical function in the autophagy pathway, which has been proposed as a target for melanoma therapy in humans." (PMID 38571883, 2024). "Both STX17 and the neighbouring NR4A3 (nuclear receptor subfamily 4, group A, member 3) gene are overexpressed in melanomas from grey horses." (PMID 32652526, 2020). "Further studies are underway to provide evidence for the direct mechanistic link of the STX17 duplication to the ERK pathway activation and melanoma development." (PMID 25413220, 2014). "However, the exact mechanism leading to melanomagenesis is still poorly understood but both STX17 and NR4A3 have possible links to tumour development including relevance for melanomas." (PMID 38571883, 2024). "Both STX17 and the neighbouring NR4A3 gene are overexpressed in melanomas from grey horses." (PMID 26354726, 2016). "When this study was conceived, we hypothesized that while the effects of STX17 are large for all four traits and ASIP has a considerable effect of melanoma, a large part of the genetic variation remains unexplained." (PMID 23408897, 2013). "In this paper we show that a 4.6 kb duplication in Syntaxin 17, associated with the Grey phenotype in horses, does not only predispose to melanoma development, as previously shown, but that a copy number expansion of the duplication may be a driving force for melanoma development." (PMID 22857264, 2012).
Legionella infection (4 papers, 2017 to 2025). "In the course of a study to reveal the mechanism underlying Legionella infection and proliferation, we incidentally discovered that this pathogen cleaves Stx17 when engulfed by FcγRII-expressing HeLa cells and macrophage-like THP1 cells." (PMID 28504273, 2017). "In this study, we show that during the first 2 h of Legionella infection STX17+ membranes derived from the ER are recruited to bacterial phagosomes causing its maturation into hybrid vacuoles bearing markers of autophagosomes and endosomes." (PMID 40506485, 2025). "The fact that Stx17 is cleaved by Lpg1137 predicts that the interactions of Stx17 with Atg14L in starved cells and Drp1 in fed cells are eliminated on Legionella infection." (PMID 28504273, 2017). "In WT Legionella infection or in SdeA-expressing cells both STX17 and SNAP29 are modified by PR-Ub." (PMID 40506485, 2025). "PR-ubiquitination of STX17 may be an important molecular mechanism by which ER membranes are recruited to the bacteria in the initial phase of Legionella infection." (PMID 40506485, 2025). "In this study, we show that Stx17 is degraded on Legionella infection." (PMID 28504273, 2017). "To determine whether translocation of STX17 to the golgi is necessary for recruitment of STX17 to bacterial phagosomes in Legionella infection, we treated cells with Brefeldin A which blocks COP-I-mediated transport between the ER and golgi at the ER exit sites." (PMID 40506485, 2025).
retinoblastoma (3 papers, 2020 to 2024). A malignant tumor that originates in the nuclear layer of the retina. "Additionally, dysregulation of STX17 expression could be linked to retinoblastoma formation, the most common malignant tumors in children." (PMID 38799985, 2024). "Using the retinoblastoma cell line Y79, it was observed that STX17 was upregulated in the context of retinoblastoma." (PMID 38799985, 2024). "Hence, maintaining the proper expression level of STX17 and its influence on autophagy regulation appears to be a crucial factor in preventing retinoblastoma formation." (PMID 38799985, 2024). "MALAT1 modulates the autophagy of retinoblastoma cell through miR-124-targated stx17." (PMID 31992960, 2020). "An illustrative example is the upregulation of STX17 expression in RPE cells exposed to oxidative stress, in corneal endothelial cell lines used as model for CHED and in retinoblastoma cell lines." (PMID 38799985, 2024).
alopecia areata (2 papers, 2022 to 2024). Loss of scalp and body hair involving microscopically inflammatory patchy areas. "In addition, autophagy-related genes that in the context of alopecia areata act at the level of melanogenesis, autoimmunity and hair follicle cycling have also been linked, such as gene encoding syntaxin 17 (STX17)." (PMID 36292745, 2022). "GWAS analyses of alopecia areata patients demonstrated associations with genes involved in autophagy, such as STX17 (Syntaxin 17)." (PMID 38649745, 2024).
Cerebral ischemia (2 papers, 2024). Restriction of arterial blood supply to the brain associated with insufficient oxygenation to support the metabolic requirements of the tissue. "This suggested that cerebral ischemia-inactivated NSF greatly suppressed reactivation of STX17 and VAMP8." (PMID 39155286, 2024). "Research has shown that there is an elevated STX17 expression in cerebral ischemia/reperfusion neurons, while suppression of STX17 exacerbates neuronal damage via the autophagy‐lysosome pathway." (PMID 39008328, 2024).
cutaneous malignant melanoma (2 papers, 2014 to 2024). "The Grey phenotype in horses, caused by a 4.6 kb duplication in intron 6 of Syntaxin 17 (STX17), is associated with a very high incidence of cutaneous melanoma, but the molecular mechanism behind the melanomagenesis remains unknown." (PMID 25413220, 2014).
gastric cancer (2 papers, 2020 to 2024). A primary or metastatic malignant neoplasm involving the stomach. "In gastric cancer, BCA2 interacts with STX17 to induce autophagosome maturation, eventually promoting gastric cancer progression." (PMID 38725852, 2024).
glioma (2 papers, 2020 to 2021). A benign or malignant brain and spinal cord tumor that arises from glial cells (astrocytes, oligodendrocytes, ependymal cells). "Overexpression of VAMP8 has also been associated with resistance to temozolomide in human glioma cells, and knockdown of STX17 in glioma cells overexpressing VAMP8 led to increased chemosensitivity." (PMID 33718194, 2021). "We chose the three genes most significantly enriched in the high-EGFR gliomas: GOSR1, TMEM167A, and STX17." (PMID 31947645, 2020).
ovarian carcinoma (2 papers, 2012 to 2025). A malignant neoplasm originating from the surface ovarian epithelium. "The presence of Syntaxin 17 and VAMP 8 in cell pellets/sediments indicates active autophagic flux, suggesting their potential role in ovarian cancer pathophysiology." (PMID 40125128, 2025).
steatosis (2 papers, 2023 to 2026). Increased lipid within the cytoplasm of cells. "In this study, STX17 was decreased in the liver of steatosis mice and STX17 protein was reduced by the loss of SRSF3." (PMID 36764525, 2023). "In contrast, transduction of miR - 300 - 3p and over-STX17 inhibit steatosis-to-MASH progressionin." (PMID 42131811, 2026). "Downregulation miR-300-3p was able to downregulate STX17 to promotes steatosis-to-MASH progression." (PMID 42131811, 2026).
viral diseases (2 papers, 2015 to 2025). "Given the significance of autophagy in the cellular clearance of pathogens and maintenance of cellular homeostasis, regulating the Stx17–Snap29–Vamp8 complex may offer new targets for controlling bacterial and viral diseases in fish." (PMID 40076623, 2025). "In addition, the recent identification of specific regulators of autophagosome maturation, such as syntaxin-17, SNAP29, and VAMP8, presents an exciting opportunity to further define the role of this critical autophagic process in limiting and/or enhancing viral infections." (PMID 25811485, 2015).
allergic asthma (1 paper, 2023). A asthma with a basis in a pathological type I hypersensitivity reaction. "A detailed, comprehensive investigation into how the PTX3/STX17 axis modulates autophagy and macrophage homeostasis in allergic asthma is certainly needed." (PMID 37957139, 2023).
asthma (1 paper, 2023). "Importantly, STX17, as a key target of PTX3-mediated macrophage homeostasis, was also more abundant in monocyte-derived macrophages isolated from asthma patients." (PMID 37957139, 2023).
atrial fibrillation (1 paper, 2024). A disorder characterized by an electrocardiographic finding of a supraventricular arrhythmia characterized by the replacement of consistent P waves by rapid oscillations or fibrillatory waves that vary in size, shape and timing and are accompanied by an irregular ventricular response. "Through these processes, elevated STX17 expression may contribute to atrial fibrillation, but its actual role and mechanism still need further in-depth study." (PMID 39135799, 2024).
Cognitive impairment (1 paper, 2024). Abnormal cognition is characterized by deficits in thinking, reasoning, or remembering. "Overexpression of Stx17 in the hippocampus markedly rescued the Meth-induced cognitive impairment and synaptic loss." (PMID 38172666, 2024). "Stx17 decrease mediated by Meth contributes to vesicle fusion defects which may ascribe to the immature autophagosomes and endosomes, leading to autophagic dysfunction and finalizes neuronal damage and cognitive impairments." (PMID 38172666, 2024).
colon cancer (1 paper, 2020). "We further examined the expression levels of LOC441461 and STX17 in colon cancer by analyzing The Cancer Genome Atlas (TCGA) database, which revealed that LOC441461 was significantly upregulated in colon cancer compared with adjacent normal tissues (p = 0.0019)." (PMID 33126743, 2020). "In this study, we assessed the expression levels of STX17 and LOC441461 in colon cancer." (PMID 33126743, 2020). "Therefore, we concluded that LOC441461 and STX17 share a bidirectional promoter but are not coexpressed in colon cancer." (PMID 33126743, 2020).
endothelial dysfunction (1 paper, 2025). In vascular diseases, endothelial dysfunction is a systemic pathological state of the endothelium (the inner lining of blood vessels) and can be broadly defined as an imbalance between vasodilating and vasoconstricting substances produced by (or acting on) the endothelium. "This switching from Parkin‐mediated to STX17‐mediated mitophagy drives endothelial dysfunction and vascular injury." (PMID 40135829, 2025). "Silencing Fis1 accelerates the switching to STX17‐mediated mitophagy, worsening endothelial dysfunction, whereas Fis1 overexpression prevents this switching, reducing ROS and apoptosis and enhancing eNOS phosphorylation." (PMID 40135829, 2025).
hepatoma (1 paper, 2022). "The requirement for ATG7 and STX17, and co-localization between APOE and autophagosome marker LC3A that we observe in HepG2 are consistent with previous work showing APOE colocalization and co-immunoprecipitation with LC3 in hepatoma cells." (PMID 34982109, 2022).
hyperhomocysteinemia (1 paper, 2025). A serious metabolic condition caused by mutations in the MTHFR gene, medications, or nutritional deficiency. "Mechanistically, it is revealed that pathogenic hyperhomocysteinemia induces homocysteinylation–ubiquitination cascades that modify Syntaxin 17 (STX17) posttranslationally, leading to its proteasomal degradation and consequent impairment of autophagic flux." (PMID 40990430, 2025).
hyperlipidemia (1 paper, 2024). "Fourth, hyperlipidemia plays an important role in the occurrence and development of AS, and further investigation is warranted to explore whether STX17 knockdown regulates AS by affecting blood lipid levels." (PMID 39008328, 2024).
inflammatory bowel disease (1 paper, 2025). A spectrum of small and large bowel inflammatory diseases of unknown etiology. "Inhibition of autophagic and mitophagic flux in platelets from mice with rheumatoid arthritis and inflammatory bowel disease is linked to low STX17 levels." (PMID 40493419, 2025).